IL6 (interleukin 6)
Diseases named in the same sentence as IL6 in open-access papers (continued):
Sharing a sentence is not in itself a finding about the gene and the disease.
sarcopenia (continued). "IL-6, TNFα, and CRP are also strongly upregulated in primary sarcopenia, suggesting a causal role of inflammageing in muscle loss." (PMID 35276842, 2022). "The present study investigated the relationship between the plasma pro-inflammatory factors TNF-α and IL-6 and the anti-inflammatory factors IL-4 and IL-10 in the elderly population and sarcopenia." (PMID 36160136, 2022). "When CRP and IL-6 were additionally offered in the stepwise procedure, probable sarcopenia lost its significance." (PMID 36476473, 2022). "There is evidence that levels of IL-6, IL-10, and the IL-6/IL-10 ratio increase in people with sarcopenia." (PMID 35250869, 2022). "Sarcopenia predominance was identified in our ND-CKD population, and was associated with lower PhA values, higher IL-6 levels, and lower serum creatinine levels." (PMID 35463026, 2022). "Protein kinase B signaling and nuclear factor κB via the secretion of transforming growth factor-β, IL-6 and TNF-α was associated with sarcopenia." (PMID 35711555, 2022). "A recent Korean study of 238 HCC patients reported that the serum level of several myokines including follistatin and IL-6 was higher in HCC patients with sarcopenia than in heathy controls, and that it was related to poor survival." (PMID 35538112, 2022). "In the current study, we investigated the association between the presence of sarcopenia and inflammatory markers including TNF-a, IL-6, and hs-CRP." (PMID 35361818, 2022). "To investigate this, we measured serum concentrations of the inflammatory cytokines IL-6, TNF-α, and IL-17A and estimated the association between IL-6 and IL-17A levels in elderly individuals with sarcopenia." (PMID 35237317, 2022). "In sarcopenia, there is an increase in the levels of inflammatory factors, including TNF-α, IL-1, and IL-6, and this increase is associated with a decrease in muscle mass." (PMID 35250869, 2022). "Positive associations were present between the severity of sarcopenia and IL-6 and IL-17A levels, whereas there was an inverse correlation between the presence of sarcopenia and the IL-10 level." (PMID 35237317, 2022). "Previous studies have shown an association of increased cytokines (e.g., TNF- α, IL-6, hs-CRP) with sarcopenia and progression of NAFLD." (PMID 35162699, 2022). "In such inflammatory conditions, the proinflammatory cytokine IL‐6 is elevated, leading to one of the essential components of sarcopenia." (PMID 36091309, 2022). "So far, studies have reported that serum levels of proinflammatory cytokines, such as TNF-α and IL-6, were increased in elderly sarcopenia cases." (PMID 35237317, 2022). "Two recent meta-analyses have been conflicting regarding TNF-α and IL-6, but both conclude elevated CRP is associated with sarcopenia." (PMID 36465176, 2022). "Sarcopenia is a reason for the impaired immunity because of the presence of IL-6, IL-15, IL-17, myokines that are responsible for the proliferation and function of the immune system." (PMID 36143878, 2022). "Although there is a clear correlation between increased peripheral IL-6 and TNF-α levels with sarcopenia, the causes and mechanisms remain partially unclear." (PMID 34093446, 2021). "Remarkably, IL-6 is highly expressed in COPD, and considered to be a biomarker of systemic inflammation, which is associated with both sarcopenia and bone loss." (PMID 34650518, 2021). "These functional changes contributed to the development of sarcopenia through anabolic resistance, chronic inflammation with elevated IL-6 and TNF-α, altered mitochondrial function, as well as oxidative stress." (PMID 33807573, 2021). "Sarcopenia has been related to nuclear factor κB and protein kinase B signaling through secretion of tumor necrosis factor-α, transforming growth factor-β and interleukin-6." (PMID 34835985, 2021).
sarcopenia (continued). "Chronic low-grade inflammation is characterized by an increase in circulating concentrations of tumor necrosis factor α (TNF-α), interleukin 6 (IL-6), IL-1 β, etc., and is present in numerous chronic diseases, including sarcopenia." (PMID 34948558, 2021). "In a previous study, cellular interleukin-6 production and serum insulin-like growth factor-1 levels were significant predictors of sarcopenia, suggesting that they play an important role as inflammatory cytokines." (PMID 33855037, 2021). "The search for common genetic factors for sarcopenia and IBD also revealed IL6, IL10, and TNF, as well as LTA, which encodes a multifunctional cytokine primarily involved in the immune functions." (PMID 34680417, 2021). "Fourthly, we included the most common inflammatory markers such as hs-CRP and IL-6, although many others (TNF-α, IL-10, etc.)that have been implicated in sarcopenia." (PMID 34911470, 2021). "Pro-inflammatory cytokines, such as interleukin (IL)-6 and tumor necrosis factor (TNF)-alpha, are associated with sarcopenia." (PMID 34403431, 2021). "To date, five studies have investigated the association of SNPs with sarcopenia; limited to VDR, IL6, ACTN3 and MSTN polymorphisms." (PMID 32076017, 2020). "The clinical data from a large population indicate that elderly sarcopenia patients have significantly elevated concentrations of proinflammatory cytokines such as IL-6 (Interleukin 6) and TNF-α (Tumour Necrosis Factor-Alpha) 8-10." (PMID 32226296, 2020). "In particular, elevated serum levels of IL-6 and TNF are markers of functional frailty and predictors of poor prognosis in the elderly, and increased levels of cellular IL-6 production are a significant predictor of sarcopenia." (PMID 33023202, 2020). "Many inflammatory markers, such as interleukin- 6 (IL-6), C-reactive protein (CRP), and tumor necrosis factor α (TNF-α), have been linked with sarcopenia." (PMID 33160322, 2020). "The involvement of IL-6 in STAT-3 signaling and its participation in sarcopenia development translates into increased weight loss." (PMID 33327591, 2020). "Sarcopenia is accompanied by muscle fat accumulation and an increase in pro-inflammatory cytokines, such as interleukin-6 (IL-6) and tissue necrosis factor alpha (TNF-α) within myocytes, which contribute to subsequent decreases in muscle mass and strength." (PMID 33222694, 2020). "It has been reported that inflammatory markers such as TNF-α and IL-6 play a key role in the occurrence of sarcopenia and these inflammatory markers are also related to depressive symptoms." (PMID 33424964, 2020). "Elevated circulating inflammatory mediators such as interleukin-6 are detectable in both PD and sarcopenia patients." (PMID 31817127, 2019). "The development of sarcopenia is correlated with raised serum levels of IL-6, an inflammatory factor." (PMID 31077169, 2019). "Biomarkers such as butyryl-cholinesterase, but also cytokines such as tumour necrosis factor alpha and interleukin-6 have been examined as chronic inflammatory biomarkers in sarcopenia." (PMID 30986265, 2019). "Biological ageing is characterized by chronic inflammation while higher levels of CRP and IL-6 are considered to be predictors of age-related sarcopenia." (PMID 31717450, 2019). "Exceptionally, the IL-6 levels in three sarcopenia and six normal samples were undetectable with a commercially available ELISA kit that can detect concentrations as low as 0.1 pg/mL." (PMID 29872072, 2018). "Studies have reported increased levels of circulating pro-inflammatory cytokines such as IL-6 and TNFα in elderly sarcopenia cases." (PMID 30541467, 2018). "The levels of inflammation cytokine IL-6, anti-inflammatory IL-10 and IL-6/IL-10 ratio were increased in elderly sarcopenia subjects." (PMID 30541467, 2018). "The practical implication of our study is that a different interpretation of IL-6 as a biomarker of aging sarcopenia is needed in men and women in future studies." (PMID 29739343, 2018).
sarcopenia (continued). "Others have observed elevated levels of circulating pro-inflammatory markers such as IL-6 and TNFα in elderly sarcopenia cases." (PMID 30541467, 2018). "Some studies have suggested a relationship between inflammatory cytokines (such as IL-6 and TNFα) and sarcopenia in humans." (PMID 29351340, 2018). "Following adjustment for confounding factors, the presence of sarcopenia was positively correlated with IL-6, IL-10, IL-6/IL-10 ratio and inversely correlated with BMI." (PMID 30541467, 2018). "In the present study, we showed that IL-6/IL-10 ratios were higher for elderly individuals with sarcopenia compared to controls." (PMID 30541467, 2018). "In the current study, we performed a cross-sectional analysis of serum concentrations of the inflammatory cytokine IL-6 and the anti-inflammatory cytokine IL-10, and IL-6/IL-10 ratios in the context of sarcopenia in elderly individuals." (PMID 30541467, 2018). "Although there are scant studies looking into this signaling cascade in OA related sarcopenia, a role of the IL-6/STAT-3/SOCS-3 axis in muscle wasting following ‘chronic low-grade inflammation’ can be foreseen." (PMID 29740336, 2018). "Here, we aim to explore the relationship between sarcopenia and the inflammatory cytokine interleukin-6 (IL-6), and the anti-inflammatory cytokine interleukin-10 (IL-10) in an elderly population." (PMID 30541467, 2018). "Higher blood levels of C-reactive protein (CRP), IL-6, and TNF-α have been associated with an increased risk of osteoarthritis, dementia, sarcopenia, and aging." (PMID 29464019, 2018). "Our observation of increased IL-6 levels in sarcopenia is supported by several analyses, in which correlations between reduced physical performance and increased levels of IL-6 and C-reactive protein (CRP) levels have been reported." (PMID 30541467, 2018). "In conclusion, we propose that elderly individuals with sarcopenia exhibit a compromised “inflammatory status” characterized by higher IL-6, IL-10 concentrations and IL-6/IL-10 ratios." (PMID 30541467, 2018). "Accordingly, higher IL-6 cut-off values must be determined in men than in women with regard to aging sarcopenia." (PMID 29739343, 2018). "This is the first study to demonstrate that a higher predictive IL-6 cut-off level should be determined for aging sarcopenia in men than in women." (PMID 29739343, 2018). "Independent associations were observed between sarcopenia and age, BMI, physical activity, nutritional risk, VFA, IL-6 levels, IL-10 levels and IL-6/IL-10 ratios." (PMID 30541467, 2018). "High levels of circulating IL-6 correlate with the development of mobility disability and high levels of IL-6 and TNF-α, either alone or together, are linked with decreased muscle mass and strength, increasing the susceptibility to sarcopenia." (PMID 30498696, 2018). "Serum IL-6 has been highlighted as a potential sarcopenia biomarker by several groups, but is yet to be statistically validated." (PMID 29872072, 2018). "Serum levels of IL-6 were higher in the sarcopenia than the normal group (1.64 ± 0.36 versus 0.86 ± 0.25 pg/ml, p = 0.015)." (PMID 29872072, 2018). "According to the findings in the study, the possible mechanisms of IL-6 in the induction of sarcopenia are as follows." (PMID 28701179, 2017). "The purpose of this study is to investigate the relationship between changes in body composition and the incidence of sarcopenia vs. inflammatory factors interleukin-6 (IL-6) and tumor necrosis factor-α (TNF-α)." (PMID 28701179, 2017). "Increased levels of inflammatory cytokines such as IL6 and TNF- alpha, as well as hsCRP, were associated with sarcopenia in the general population and patients with ESRD." (PMID 28448584, 2017). "IL-6 plays an important role in the pathogenesis of several chronic diseases including sarcopenia by regulating inflammatory and metabolic functions." (PMID 27382188, 2016). "IL‐6 levels are strongly related to muscle strength, functional decline, and sarcopenia in older adults." (PMID 27325353, 2016).
sarcopenia (continued). "Further studies are needed to elucidate how IL-6 are involved in the pathogenesis of age-related sarcopenia." (PMID 29259690, 2016). "Recent findings suggest that some inflammatory cytokines including TNF-α and IL-6 are involved in pathophysiology of age-related sarcopenia." (PMID 29259690, 2016). "IL-6 reflected both adiposity-, but also sarcopenia-related inflammation; and suPAR was a marker of sarcopenia-related inflammation." (PMID 26244048, 2015). "If IL-6 was acting as mediator for CMV infection (i.e. CMV infection causes inflammation, raising IL6 levels, which causes increased sarcopenia), we would expect a correlation between the two variables." (PMID 23938060, 2013). "In this study we investigated the relationship between latent CMV infection, IL-6 level and markers of sarcopenia (muscle size and strength) in a healthy older cohort of community-dwelling men and women." (PMID 23938060, 2013). "IL-6 was later found to correlate with lower muscle mass and strength, further implicating it in the progression of sarcopenia." (PMID 21832306, 2011). "These cytokines, viz., IL-6, TNF-α, and IL-1β, activate muscle-specific protein degradation pathways through E3 ubiquitin ligases TRIM63 and FBXO32, linking NSCLC progression to cancer-associated sarcopenia." (PMID 42278237, 2026). "We propose that IL‐6 signaling may shift toward the proinflammatory profile and participate in sarcopenia progression when skeletal muscle function gradually decreases during aging." (PMID 39764565, 2025). "Furthermore, apelin implicated in sarcopenia and inflammatory biomarkers (CRP, TNF-α, IL-6, IL-8, and LTB4) were also measured in the serum." (PMID 40649397, 2025). "On the contrary, IL-6 is a myokine that is increased in patients who present sarcopenia due to aging or secondary to pathology, and it is used as an indicator of the severity of sarcopenia." (PMID 39857418, 2025). "Additionally, other myokines, such as interleukin 6 (IL-6) and brain-derived neurotrophic factor (BDNF), have been implicated in the modulation of sarcopenia." (PMID 40076821, 2025). "Moreover, a cross-sectional study involving individuals aged 90 years and older revealed that interleukin-6 (IL-6), interleukin-1 receptor antagonist (IL-1Ra), and C-reactive protein (CRP) were correlated with the risk of sarcopenia." (PMID 40735206, 2025). "Indeed, in conditions of axonal injury, muscle injury, muscle stress (e.g., exercise) and atrophy (e.g., sarcopenia), increases in the muscle expression of IL6 are correlated with increased levels of circulating IL6." (PMID 39851451, 2025). "This chronic, low-grade inflammatory state is recognized as a key pathological mechanism underlying sarcopenia, where inflammatory mediators like TNF-α and IL-6, activated through the NF-κB signalling pathway, inhibit muscle protein synthesis and accelerate muscle protein breakdown." (PMID 40678078, 2025). "Similarly, higher TNF-α levels independently correlated with increased sarcopenia risk (OR=1.380, 95% CI: 1.073–1.755, P=0.012), indicating that both IL-6 and TNF-α were independently linked to sarcopenia." (PMID 40265008, 2025). "These revealed an association between ACTN3 and VDR gene variants and sarcopenia, while no such association was observed for IL6 variants and a specific MSTN variant linked to strength in athletes." (PMID 40772803, 2025). "Consistent with this speculation, clinical studies showed that levels of IL‐6 are dramatically upregulated in patients with sarcopenia after adjustment for potential confounders such as BMI and visceral fat tissue." (PMID 39764565, 2025). "There is some evidence that the link between PD and sarcopenia could be driven by neuroinflammation mediated by interleukin-6 (IL-6)." (PMID 40553423, 2025). "Additionally, inflammatory cytokines such as IL‐1, IL‐6, and TNF‐α, which are associated with anorexia and weight loss, are used for prognosing cancer cachexia and sarcopenia." (PMID 39764565, 2025).
sarcopenia (continued). "The proinflammatory effects of IL‐6 signaling contribute to age‐induced chronic low‐grade inflammation and may participate in the pathogenesis of sarcopenia." (PMID 39764565, 2025). "Adipose tissue serves not only as an energy store but also as an active endocrine organ capable of releasing inflammatory cytokines, such as TNF-α and interleukin-6 (IL-6), which can contribute to muscle breakdown, inhibit muscle synthesis, induce muscle atrophy, and ultimately lead to sarcopenia." (PMID 40255379, 2025). "Studies have shown that elevations in IL-6 and CRP may particularly play a role in the inflammatory link between sarcopenia and cardiovascular risk." (PMID 40034988, 2025). "The role of IL-6 in cachexia-related sarcopenia has been previously discussed in this section and elevated levels of TNF-α, IL-6 as well C-reactive protein (CRP) have been detected in sarcopenic people, further suggesting a link between systemic inflammation and muscle degeneration." (PMID 40181329, 2025). "Patients with aging sarcopenia have higher blood concentrations of IL-6 than healthy individuals, and elevated plasma IL-6 may increase fat deposition within skeletal muscle." (PMID 40801027, 2025). "IL-6 and TNF-α have been repeatedly shown to be associated with sarcopenia." (PMID 40869107, 2025). "The levels of inflammatory markers such as TNF-α, high-sensitivity C-reactive protein (hs-CRP), and interleukin (IL)-6 are above average in patients with lower muscle strength, suggesting that sarcopenia might have a relationship with MAFLD." (PMID 40429815, 2025). "Preoperative assessment of IL‐6 and GDF‐15 levels, alongside evaluation of sarcopenia, could enhance risk stratification and inform personalised treatment strategies." (PMID 41380167, 2025). "In older adults, IL-6 also correlates with sarcopenia in a sex-dependent manner." (PMID 41208983, 2025). "Together, these findings suggest that sarcopenia may undermine the effectiveness of immune checkpoint inhibitors by disrupting the IL-15/IL-6 balance and exacerbating T-cell dysfunction." (PMID 41019539, 2025). "Additionally, cytokines produced from cancer cells, such as PTHrP, interleukin (IL)-1, IL-6, and IL-8, create and activate osteoclasts through activating the RANK/RANKL receptors, and subsequently, NF-κB, which leads to muscle loss and sarcopenia." (PMID 40375934, 2025). "IL-6 and sIL-6R are important factors in the regulation of inflammation, but their effects on muscle mass and function suggest that the relationship for IL-6 and sIL-6R with sarcopenia is complex and may be mediated by other factors." (PMID 38750566, 2024). "Furthermore, studies have highlighted the correlation between inflammatory status and sarcopenia, showing a positive relationship between levels of C-reactive protein, interleukin-6, and sarcopenia." (PMID 39797093, 2024). "NLRP3 and Myd-88 are key orchestrators of chemotherapy-related cardiovascular diseases (CTRCD) and sarcopenia; cytotoxic properties are principally mediated by high levels of pro-inflammatory cytokines and chemokines, such as IL-1β, IL-6, IL-8, CXCL-2, TGF-β, IL-18 and others." (PMID 38672567, 2024). "IL-6 also acts as a member of the SASP, causing sarcopenia through proinflammatory effects." (PMID 38774874, 2024). "In murine models of sarcopenia, coffee intake increased muscle mass, accelerated the regeneration of injured muscles and decreased some proinflammatory markers such as the interleukins IL-1α, IL-6, and tumor necrosis factor alpha (TNF-α)." (PMID 39275165, 2024). "The disruption of the normal muscle physiology, as in the case of sarcopenia, has been shown to lead to abnormal myokine signaling culminating in a proinflammatory environment characterized by impaired IL-6 signaling, increased TNF-alpha production and decreased IL-1ra and IL-10 levels." (PMID 38698153, 2024). "Previous research has extensively examined the role of interleukin 6 (IL-6) in sarcopenia." (PMID 38750566, 2024).